WNT11 (Wnt family member 11)
Diseases named in the same sentence as WNT11 in open-access papers (continued):
Sharing a sentence is not in itself a finding about the gene and the disease.
prostate carcinoma (continued). "In prostate cancer cells, Wnt-11 and several FZDs activated ATF2-dependent transcription." (PMID 29717114, 2018). "Wnt11 has been shown to play a role in invasion and metastasis of prostate cancer." (PMID 29717114, 2018). "Previous studies have reported the involvement of Wnt-11 in prostate cancer migration and invasion." (PMID 29717114, 2018). "Wnt-11 protein levels were found to be elevated in human prostate tumors compared to benign prostatic hypertrophy specimens and it induced neuroendocrine-like differentiation in prostate cancer cells." (PMID 22325146, 2012). "Finally, it shows that Wnt-11 is required for prostate cancer cell survival and promotes prostate cancer cell invasion." (PMID 20219091, 2010). "In addition, it demonstrates that Wnt-11 is both necessary and sufficient for induction of neuroendocrine-like differentiation in prostate cancer cells and that this requires PKA activity." (PMID 20219091, 2010). "Moreover, Wnt-11 and AR are co-expressed in other prostate cancer cell lines and in prostate tumour cells." (PMID 20219091, 2010). "Following the selection of the prostate cancer dataset from TCGA, we ran UCSC Xena to evaluate the relationship between Wnt11 and the Gleason score." (PMID 32182839, 2020). "FZD4 expression was higher in androgen-independent and metastatic prostate cancer cell lines, while FZD2 was upregulated in hormone-depleted LNCaP cells, similar to WNT11." (PMID 29717114, 2018). "Taken together, these observations support a model in which FZD8, by interacting both with Wnt-11 and TGFβRI, is able to play a pivotal role in integrating Wnt and TGF-β signals to drive EMT and invasion in prostate cancer." (PMID 29717114, 2018). "After identifying Wnt receptors with increased expression in prostate cancer, immunofluorescence assays were used to determine which FZD receptors, when transfected, co-localized with Wnt-11." (PMID 29717114, 2018). "Together, these results indicate that Wnt-11 not only plays roles in NED and survival of prostate cancer cells, but also in their ability to migrate and invade." (PMID 20219091, 2010). "Here, we have further investigated the function of Wnt-11 and show that it promotes NED in a PKA-dependent manner and promotes prostate cancer cell survival, migration and invasion." (PMID 20219091, 2010). "Moreover, Wnt-11 leads to neuroendocrine differentiation of different prostate cancer cell lines and orchestrates many proteins, including PKC, JNK, NF-κB, Rho, PKA, PI3K, and crosstalk between Wnt-11 and TGF-β was demonstrated." (PMID 33557112, 2021). "It has been demonstrated that ERRα expression is correlated with castration-resistant prostate cancer, and it could promote tumor progression by targeting a number of cancer-related genes, including VEGF-A, WNT5A and TGFβ1, and WNT11 and HIF-1α." (PMID 33014785, 2020). "In addition, Wnt-11 increased ATF2-dependent gene reporter activity in both cell lines, a similar extent as has been observed in prostate cancer cell lines." (PMID 31261741, 2019). "In prostate cancer cells, gene reporter assays have been used to show that Wnt-11 increases non-canonical Wnt signaling, measured using an ATF2-dependent luciferase reporter, and inhibits canonical Wnt (β-catenin/Tcf-dependent) signaling." (PMID 31261741, 2019). "FZD4 mRNA levels were upregulated in prostate tumor datasets but FZD4 silencing did not affect Wnt-11 activation of ATF-2-dependent transcription and FZD4 did not colocalize with Wnt-11, so FZD4 is unlikely to transduce Wnt-11 signals in prostate cancer." (PMID 29717114, 2018). "Several Wnt co-receptors were highly expressed in the majority of the prostate cancer lines examined, although none of them matched the WNT11 expression profile." (PMID 29717114, 2018).
prostate carcinoma (continued). "Wnt-11 is found to be upregulated in metastatic disease, and more importantly, it has been shown that it involves in TGF-β signaling pathways during the epithelial-to-mesenchymal transition (EMT), which is important for prostate cancer cell migration and invasion." (PMID 32182839, 2020). "Notably, WNT11 expression in HT29 cells, although low among CRC cell lines, was similar to what we observe in prostate cancer cell lines, where it promotes invasion, suggesting that Wnt-11 in HT29 cells may be functional." (PMID 31261741, 2019). "For example, WNT11 expression appears to be upregulated by androgen depravation treatment (ADT), and WNT11 expression may promote neuroendocrine differentiation in prostate cancer." (PMID 30987640, 2019). "However, it is not known which of them mediate the response to Wnt-11 and play a role in prostate cancer." (PMID 29717114, 2018). "Furthermore, Wnt3a treatment increased the self-renewal of putative PCSCs independent of androgen signaling, and Wnt11 expression was shown to be inversely correlated to AR expression in prostate cancer cell lines and primary cultures." (PMID 24212796, 2011). "However, the prevalence of increased expression of Wnt-11 in patient tumours and the functions of Wnt-11 in prostate cancer cells were not known." (PMID 20219091, 2010). "However, we previously showed that Wnt-11 does not inhibit AR activity in androgen-independent AR-positive prostate cancer cell lines." (PMID 20219091, 2010). "However, the receptors that transduce Wnt-11 signals in prostate cancer are not known." (PMID 29717114, 2018). "In summary, Wnt-11 has similar effects on canonical and non-canonical Wnt signals, as measured by gene reporter assay, in CRC cells as in prostate cancer cells." (PMID 31261741, 2019).
colorectal cancer (9 papers, 2019 to 2025). A primary or metastatic malignant neoplasm that affects the colon or rectum. "Analysis of colorectal cancer gene expression databases associated WNT11 mRNA expression with increased likelihood of metastasis in a subset of patients." (PMID 31261741, 2019). "Thus, it appears that patients with high Wnt-11 have fewer co-morbidities, which may confound an association of Wnt-11 with increased mortality resulting from colorectal cancer." (PMID 31261741, 2019). "Elevated serum WNT11 levels correlate with poor prognosis and immune exclusion signatures in patients with colorectal cancer LM, indicating its potential utility as a minimally invasive diagnostic and predictive tool." (PMID 41426343, 2025). "Mechanistically, hsa_circ_0039933 targeted hsa-miR-204-5p to increase the expression of wnt11, leading to the activation of the Wnt pathway, thereby promoting the proliferation of colorectal cancer cells." (PMID 37587207, 2023). "Immunohistochemical analysis of Wnt-11 in a cohort of 357 colorectal cancer patients found significantly higher Wnt-11 levels in tumors, compared with benign tissue." (PMID 31261741, 2019). "The expression of the secreted factor Wnt-11 is elevated in several types of cancer, including colorectal cancer, where it promotes cancer cell migration and invasion." (PMID 31261741, 2019). "Expression of Wnt-11 in colorectal cancer cell lines expressing low endogenous Wnt-11 inhibited β-catenin/Tcf activity and increased ATF2-dependent transcriptional activity." (PMID 31261741, 2019). "The study also identifies FZD6, RYK, and PTK7 as candidate receptors for Wnt-11 in colorectal cancer." (PMID 31261741, 2019). "Genes WNT11 and THPO were reported to be associated with ovarian cancer and colorectal cancer, respectively." (PMID 31640538, 2019). "WNT11 gene silencing and antibody-mediated inhibition of Wnt-11 in colorectal cancer cell lines expressing high Wnt-11 reduced their capacity for invasion." (PMID 31261741, 2019). "This work revealed the potential molecular mechanism of HD–SB for the treatment of colorectal cancer, which was to inhibit the Wnt signaling pathway through the hsa_circ_0039933/hsa-miR-204-5p/wnt11 axis, then suppressing proliferation, migration, and invasion in the colorectal cancer cell." (PMID 37587207, 2023). "It was demonstrated that HD-SB down-regulated the expression of wnt11 through the hsa_circ_0039933/hsa-miR-204-5p axis, thereby inhibiting the Wnt signaling pathway and reducing the proliferation, invasion, and migration ability of colorectal cancer cells." (PMID 37587207, 2023). "The results are of interest because they show location- and gender-specific differences in Wnt-11 protein levels in colorectal cancer and because they suggest that antibody-mediated inhibition of Wnt-11 should be considered as a possible approach for future therapies for metastatic CRC." (PMID 31261741, 2019). "Together, these observations suggest that Wnt-11 could be a potential target for the treatment of patients with invasive colorectal cancer." (PMID 31261741, 2019). "The combined expression of WNT11 and FZD6 could be predictive of a worse clinical outcome for patients with colorectal cancer." (PMID 33618667, 2021). "The dependence of WNT activity on cellular context confirms this; in particular, it has been shown that some noncanonical ligands, such as WNT11, can activate canonical WNT/β-catenin in a particular colorectal cancer cellular context." (PMID 37345102, 2023).
melanoma (8 papers, 2016 to 2023). A malignant, usually aggressive tumor composed of atypical, neoplastic melanocytes. "Circos plots further showed that hsa-miR-122-5p, which was profoundly upregulated in our metastatic UM samples, is implicated in stemness of cells and melanoma development by targeting Nodal growth differentiation factor (NODAL), SOX11, WNT11 and CDK4." (PMID 36619870, 2022). "WNT11 was shown to play an important role in neural crest migration and appears to have a role in the aberrant activation of Wnt signaling in melanoma." (PMID 35052351, 2021). "We find that FZD7 receptor downstream of WNT11/WNT5B ligands is upregulated during melanoma progression and we show this receptor sustains amoeboid behaviour." (PMID 33082334, 2020). "We have shown that WNT11 can promote amoeboid features in melanoma cells in a paracrine manner." (PMID 33082334, 2020). "Furthermore, WNT11 stimulated RhoA activity and downstream Myosin II levels in melanoma cells, but this effect was lost when DAAM1 was silenced." (PMID 33082334, 2020). "(E, E′, E′′) Culture media from melanoma A375, A375 IV, and A2058 cell lines were collected after 48 hr and analyzed by western blotting for the presence of WNT5A (E′) and WNT11 (E′′)." (PMID 34702444, 2021). "In particular, WNT11-cognate receptor FZD7 and its co-receptor RYK were both consistently upregulated in metastatic melanomas in most of the studies." (PMID 33082334, 2020). "In melanoma cell lines, knockdown of WNT5B and WNT11 reduced the formation of melanospheres." (PMID 36982422, 2023). "Additionally, a reduction in the invasiveness of melanoma cells in a collagen invasion assay upon knockdown of WNT5B and WNT11 was observed." (PMID 36982422, 2023). "WNT3 and WNT5A were detected at a much higher level than WNT8 and WNT11, so we investigated further whether WNT3 and WNT5A signal through FZD7 in melanoma cells." (PMID 26808375, 2016). "WNT11, WNT9A and WNT4 were tumor negative WNTs, which were abundant in normal tissues, while declining in many tumors including melanoma, sarcoma, breast adenocarcinoma and colorectal adenocarcinoma." (PMID 35850748, 2022). "We propose here that non-canonical WNT11/5B-FZD7-DAAM1 axis crucially and specifically controls tumour initiation potential in melanoma by promoting ROCK1/2-Myosin II driven amoeboid proliferative and invasive phenotype." (PMID 33082334, 2020).
pulmonary fibrosis (5 papers, 2022 to 2025). Chronic progressive interstitial lung disorder characterized by the replacement of the lung tissue by connective tissue, leading to progressive dyspnea, respiratory failure, or right heart failure. "Recent studies have implicated Wnt2 and Wnt11 in the progression of cardiac and pulmonary fibrosis." (PMID 38267432, 2024). "In this study, we investigated the impact of Wnt11 signaling in fibroblasts and pulmonary fibrosis in vivo using a fibroblast-specific Wnt11 knockout model." (PMID 41516227, 2025). "By applying the loss-of-function experiment, the COL20A1, COL27A1, and WNT11 were confirmed as key profibrotic regulators of EMT and development of pulmonary fibrosis." (PMID 40034336, 2025). "Further supporting this mechanism, recent studies demonstrate elevated Wnt11 expression in fibrotic lungs alongside the established role of TGFβ in BLM-induced pulmonary fibrosis in mice." (PMID 41516227, 2025). "We demonstrate that Wnt11 promotes bleomycin-induced lung fibrosis and that fibroblast-specific depletion of Wnt11 significantly reduces fibrotic remodeling." (PMID 41516227, 2025). "To further consolidate the findings of our study, we analyzed the expression levels of COL20A1, COL27A1, and WNT11 in patients with pulmonary fibrosis." (PMID 40034336, 2025). "Wnt11 is upregulated in both kidney and pulmonary fibrosis, and it has been shown to promote myofibroblast and cardiomyogenic differentiation through c-Jun/JNK pathway, acting in both autocrine and paracrine manners." (PMID 41516227, 2025). "Our results show that components of the non-canonical Wnt pathway are upregulated in bleomycin-induced pulmonary fibrosis and that in vivo depletion of Wnt11 in mouse lung fibroblasts significantly reduces lung fibrosis." (PMID 41516227, 2025). "The concordance between our in vivo phenotype and fibroblast-intrinsic in vitro findings supports a primary role for fibroblast-derived Wnt11 in regulating lung fibrosis in this bleomycin model of lung fibrosis." (PMID 41516227, 2025). "The specific role of Wnt11 in fibroblasts during pulmonary fibrosis, as well as its function in cellular crosstalk, remains unclear." (PMID 41516227, 2025). "In addition, the WNT11 expression was significantly higher in patients with pulmonary fibrosis as compared with the control group in GSE40839 dataset." (PMID 40034336, 2025). "Importantly, significantly higher expression of COL27A1 and WNT11 was found in patients with pulmonary fibrosis." (PMID 40034336, 2025). "(D) RNA-seq analysis shows upregulation of WNT5A and WNT11, non-canonical WNTs associated with pulmonary fibrosis (* p<0.05, ** p<0.01, *** p<0.001, **** p<0.0001, DEseq2 pairwise contrast statistics)." (PMID 35559731, 2022). "As the Collagen-I plays a crucial role in fibrogenesis and the pulmonary fibrosis is characterized by its accumulation, the reduction in Collagen-I deposition caused by knocking out the COL20A1, COL27A1, and WNT11 may indicate a potential direction for pulmonary fibrosis treatment." (PMID 40034336, 2025). "Our results demonstrate that the COL20A1, COL27A1, and WNT11 are key profibrotic regulators of IPF, and the knockout of these genes attenuated the TGF-β1-induced EMT and pulmonary fibrosis in vitro." (PMID 40034336, 2025). "Altogether, all of our findings demonstrate that the COL20A1, COL27A1, and WNT11 serve as key profibrotic regulators and may play a crucial role in regulating the TGF-β1-induced EMT and the pathogenesis of pulmonary fibrosis." (PMID 40034336, 2025). "Together, these findings identify non-canonical Wnt11 as a regulator of myofibroblast differentiation and lung fibrosis." (PMID 41516227, 2025).
colon cancer (4 papers, 2009 to 2021). "Within the WNT pathway, individual genes evidencing association with colon cancer were WNT11 (P = 0.014) and TCF7L2 (P = 0.045)." (PMID 29986644, 2018). "Wnt-11 was also higher in rectal tumors than in colonic tumors, contrasting with the normal colon in mice, where Wnt11 gene expression is higher in the proximal colon than in the distal colon." (PMID 31261741, 2019). "Elevated Wnt-11 levels occurred more frequently in rectal tumors than in colonic tumors and in tumors from women than men." (PMID 31261741, 2019). "A difference in rectal and colonic tumors could reflect differential regulation of Wnt-11 by the tumor environment, for example, WNT11 gene expression can be induced by hypoxia and by bacterial infection, which may differ in the colon and rectum." (PMID 31261741, 2019). "Although we did not observe significant location-specific differences in WNT11 expression in CRC datasets, analysis of TGCA and GTEx data using a higher cut-off found a more robust increase in WNT11 in rectal tumors than in colonic tumors (R.K., unpublished observations)." (PMID 31261741, 2019). "In addition, elevated Wnt-11 was more prevalent in rectal than in colon cancer (p = 0.04)." (PMID 31261741, 2019). "We have detected Wnt11 mRNA in seven colon cancer cell lines (data not shown)." (PMID 19773752, 2009).
hepatocellular carcinoma (4 papers, 2015 to 2022). A malignant tumor that arises from hepatocytes. "It should be noted however that another report suggests a tumor suppressor role for WNT11 in hepatocellular carcinoma cells." (PMID 26861754, 2016). "However, Wnt11 levels are low in hepatocellular carcinomas than that in normal liver, leading to a model in which Wnt11 is a tumour suppressor." (PMID 25999350, 2015). "Previous studies show that noncanonical Wnt11 inhibits hepatocellular carcinoma cell proliferation and migration." (PMID 27329839, 2016).
Obesity (4 papers, 2020 to 2025). Accumulation of substantial excess body fat. "The greatest increases in methylation in Wnt11, Celsr2 and Adcy3 could indicate future routes of investigation to elucidate the potential of PEA in NASH treatment, especially given their associations with obesity and diabetes." (PMID 40153413, 2025).
ovarian carcinoma (4 papers, 2019 to 2024). A malignant neoplasm originating from the surface ovarian epithelium. "We found that a low expression level of CDKN2B and WNT11 was associated with longer survival in ovarian cancer patients, while high expression levels of SMAD3, ZFYVE16, BMP6, LEFTY1, and DVL2 were significantly associated with poor survival." (PMID 38403634, 2024). "On the other hand, Wnt11 is considered to be a tumour‐suppressor protein that inhibits tumour cell migration, invasion and adhesion in ovarian cancer, endometrial cancer and liver cancer." (PMID 33417298, 2021). "Multicellular spheroids of ovarian carcinoma, prepared with the SKOV-3 cell line, have been used to better understand the role of Wnt11 on the expression of integrins and cadherin." (PMID 38254117, 2024). "In these 3D models, Wnt11 was shown to negatively regulate ITGB2, ITGB6 and EpCAM while impeding the attachment of the multicellular spheroids to an ECM substrate, suggesting a role of this molecule in ovarian cancer progression." (PMID 38254117, 2024).
renal fibrosis (4 papers, 2016 to 2025). A final common manifestation of a wide variety of chronic kidney diseases characterized by glomerulosclerosis and tubulointerstitial fibrosis. "With regard to the WNT11, a previously published study reported a remarkable increase of WNT11 in renal epithelial cells following TGF-β1 treatment, and the WNT11 interacted with TGF-β for the development of renal fibrosis." (PMID 40034336, 2025). "Wnt11 promotes renal fibrosis by cooperating with TGF-β signaling through non-canonical Wnt signaling." (PMID 33391533, 2021). "Although the function of Wnt11 and Wnt6 in liver fibrosis was unknown, Wnt11 was shown to enhance the expression of mesenchymal markers, such as Zeb1, Snail1, Pai1 and α-SMA, in response to the TGF-β signaling in renal fibrosis, and Wnt6 was reported to be downregulated during renal fibrogenesis." (PMID 27322257, 2016).
basal cell carcinoma (3 papers, 2020 to 2025). A carcinoma involving the basal cells.